RNU6-926P (RNA, U6 small nuclear 926, pseudogene)
Gene: Small nuclear RNA gene on chromosome 21 (26,190,707 to 26,190,813, forward strand). Ensembl gene ENSG00000206802.
Homologues: Orthologues: chimpanzee U6 (95% identical), macaque U6 (93% identical), pig U6 (82% identical), pig U6 (81% identical), rat U6 (76% identical), rabbit U6 (75% identical), dog U6 (68% identical). Paralogues in human: RNU6-1060P (86% identical), RNU6-116P (86% identical), RNU6-338P (86% identical), RNU6-47P (86% identical), RNU6-708P (86% identical), RNU6-1011P (85% identical), RNU6-12P (85% identical), RNU6-13P (85% identical), RNU6-187P (85% identical), RNU6-32P (85% identical), RNU6-33P (85% identical), RNU6-41P (85% identical), and 1288 more.